YY1 (YY1 transcription factor)
Diseases named in the same sentence as YY1 in open-access papers (continued):
Sharing a sentence is not in itself a finding about the gene and the disease.
melanoma (continued). "Interestingly, while autophagy may either promote or suppress tumor growth, in melanoma cells, YY1 was shown to coordinate with Transcription factor EB (TFEB) and regulate genes involved in autophagy and lysosomal biogenesis." (PMID 31824839, 2019). "However, YY1 plays an oncogenic role in some cancers such as melanoma." (PMID 28485541, 2017). "To test this hypothesis, we used si-YY1 to inhibit the endogenous YY1 activity in melanoma cells." (PMID 26104682, 2015). "Taken together, these results suggest that YY1 might play a regulatory role in melanoma cell growth and migration, especially for the melanomas that do not harbor a BRAFV600E mutation." (PMID 26104682, 2015). "Furthermore, to test whether the regulation of YY1 on RYBP expression is mediated by miR-9 in melanoma cells, we performed a “rescue” assay with the combination of si-YY1 and miR-9 inhibitor in WM1791C cells." (PMID 26104682, 2015). "Therefore, its regulation in cancer along with the development of new therapeutic targets of YY1 may represent promising tools against melanoma therapy." (PMID 26104682, 2015). "Recently, the possible role of the Yin Yang 1 (YY1) transcription factor in the pathogenesis and drug resistance of malignant melanoma is considered." (PMID 35719931, 2022). "Human melanoma sections stained by immunofluorescence showed activation of the p38MAPK/JNK pathway in tumor-infiltrating lymphocytes, which drives YY1 expression, leading to PD1 upregulation." (PMID 35719931, 2022). "We found that YY1-knockdown melanoma cells were more sensitive to TGF-β1 stimulation, in that YY1 knockdown cells treated with TGF-β1, boosted the expression of the EMT genes FN1, CDH2, ZEB1, SNAI1 and VIM, among others." (PMID 35693944, 2022). "YY1 acts upstream MITF and cMYC pathways and governs multiple metabolic pathways and protein synthesis in neural crest stem cells and melanoma." (PMID 34638331, 2021). "We, therefore, looked at the levels of YY1 and acetylated protein in FKBP51-silenced melanoma cells, cultured in the absence or presence of TSA." (PMID 34589486, 2021). "Similar to SOX10 and YY1, SALL4 is upregulated in melanoma cells and is essential for primary tumor formation and proliferation." (PMID 34417458, 2021). "On the other hand, suppression of Yin Yang 1 (YY1), which is a cofactor of TFEB and contributes to the regulation of genes related to autophagy and lysosome biogenesis, evoked enhanced anti-melanoma efficiency of vemurafenib both in vitro and in vivo." (PMID 32340261, 2020). "Despite the fact that YY1 ChIP-seq was performed in a distinct melanoma line, we identified 2853 sites where YY1 co-localized with MITF and 3060 SOX10-YY1 co-occupied sites." (PMID 25803486, 2015). "As SOX10, YY1, TFAP2A, and ETS1 all have important roles in melanocytes and/or melanoma, the MAREs identified here define a combinatorial signature of TFs critical for gene regulation in this lineage." (PMID 25803486, 2015). "To globally identify YY1 target genes in the melanocytic lineage, we performed a ChIP-seq analysis in MALME-3M melanoma cells." (PMID 22570637, 2012). "Re-analysis of published ChIP-seq data did not reveal a direct regulatory effect of YY1 on invasiveness and phenotype switching genes in melanoma." (PMID 35693944, 2022). "The combined data suggests that TGF-β signal activation contributes to the enhanced invasiveness program observed upon YY1 knockdown by synergistically boosting the expression of classical EMT genes and influencing other important players in melanoma phenotype switching." (PMID 35693944, 2022). "The fixed chromatin was immunoprecipitated with an anti-YY1 antibody from A375 melanoma cells (silenced or not for FKBP51) and analyzed by RT-qPCR." (PMID 34589486, 2021). "In addition to repressing miR-9, YY1 also has been shown to directly bind to snail gene enhancer region and activate snail transcription and thus promote EMT and metastasis of melanoma cells." (PMID 31824839, 2019).
melanoma (continued). "Additionally, the expression of RYBP in melanoma cells was negatively regulated by miR‐9, which was suppressed by the RYBP binding protein, YY1." (PMID 29383875, 2018). "Although the role that YY1 plays in different human types of cancer has been reported, its biological and mechanistic significance in melanoma has not been well defined." (PMID 26104682, 2015). "We therefore performed expression profiling analysis using MALME-3M melanoma cells with or without YY1 knockdown." (PMID 22570637, 2012). "In addition, YY1 is also not always highly expressed in tumors, such as melanoma, YY1 expression is significantly lower in metastatic melanoma than in normal melanocytes." (PMID 37081988, 2023). "In this report, it was speculated that YY1 mediated autophagy might provide resistance to BRAF inhibitor vemurafenib, and this notion was supported by the observation that suppression of YY1 sensitizes melanoma cells to vemurafenib both in vitro and in vivo." (PMID 31824839, 2019). "Furthermore, RYBP and YY1 were found to co-occupy several target promoters/enhancers of YY1 to silence their expression, thereby a YY1 ~ miR-9 ~ RYBP feedback regulatory loop might be existed in melanoma cells." (PMID 26104682, 2015).
colorectal cancer (42 papers, 2015 to 2026). A primary or metastatic malignant neoplasm that affects the colon or rectum. "Collectively, these results indicate that YY1 is a key transcription factor of OXCT1 in colorectal cancer." (PMID 41492470, 2026). "In colorectal cancer, YY1 was shown to transcriptionally regulate transmembrane protein 97 (TMEM97), leading to downstream modification of GSK3β via phosphorylation." (PMID 38539569, 2024). "ARAP1-AS1, which shows high expression in colorectal cancer cells and tissues, can be enhanced by YY1 transcription factor to facilitate tumor cell migration, invasion, and epithelial-mesenchymal transition." (PMID 35291911, 2022). "Taken together, NEAT1 sponged miR-216b to activate YY1 to accelerate the ability of cell viability, apoptosis, and invasion on colorectal cancer cells." (PMID 36262350, 2022). "It has been found that miR-4262 can be sponged by circAGFG1, and it can regulate the YY1/CTNNB1 axis to drive colorectal cancer metastasis." (PMID 33821195, 2021). "As a result, hsa-miR-193a-5p can obviously inhibit the expression of YY1 and NF-кB-P65 in colorectal cancer cells." (PMID 34336703, 2021). "The tumorigenic potential of YY1 in colon cancer has been demonstrated with both overexpression and knock-down experiments in colorectal cancer cell lines such as HCT116, LOVO and DLD." (PMID 31217904, 2019). "Silencing of YY1 resulted in reduced proliferation and induction of apoptosis, whereas overexpression enhanced proliferation and inhibited apoptosis of colorectal cancer cells." (PMID 31217904, 2019). "Similarly, phosphorylation of OTUD3 enhances its binding affinity to the transcription factor YY1, thereby stabilizing YY1 and promoting colorectal cancer (CRC) progression." (PMID 39678489, 2024). "A study conducted by Pothoulakis and colleagues on colorectal cancer (CRC) patients revealed that upregulation of YY1 resulted in the repression of host immunosurveillance mechanisms through Fas downregulation on tumor cells, and that mRNA expression levels of YY1 and Fas were inversely correlated." (PMID 38539569, 2024). "It has been detected that YY1 was highly expressed in colorectal cancer (CRC)." (PMID 36880159, 2023). "Colorectal cancer remains one of the most common cancers with a global disease burden, with one of the highest morbidity and mortality rates among cancers. luciferase reporter gene detection showed that YY1 had strong activity on the ARAP1-AS1 promoter." (PMID 36626426, 2022). "It is suggested that lnc-TLCD2-1 may target YY1/NF-кB -p65 axis by miR-193a-5p-targeting to regulate the environment of tumor immunoinvasion in colorectal cancer, then modulate the radiosensitivity of CRC and affect the clinical prognosis of CRC patients." (PMID 34336703, 2021). "Recent studies have shown that YY1 expression can promote the proliferation of colorectal cancer." (PMID 34336703, 2021). "Finally, bioinformatics analysis revealed a significant correlation between YY1 expression and immune cell infiltration in colorectal cancer." (PMID 34336703, 2021). "YY1 contributes to colorectal cancer development by the miR-526b-3p/E2F1 signaling." (PMID 35004266, 2021). "Transcription factor YY1 was found to regulate lncRNA expression in colorectal cancer, but whether it regulated SNHG17 in glioma was still unclear." (PMID 32009853, 2020). "Functional studies have demonstrated a damaging effect via binding disruptions of the TF YY1 and impaired activity of the APC promoter in gastric and colorectal cancer cell lines." (PMID 40470206, 2025). "Due to sequence and functional conservation between human and mouse YY1 proteins, we chose wild-type HCT116, a human colorectal cancer cell line, as the host." (PMID 39460630, 2024). "Over-expressed OTUD3 inhibited YY1 degradation, thereby increasing YY1 protein levels, whereas OTUD3 knockdown or knockout promoted YY1 degradation, thereby decreasing the proliferation of colorectal cancer (CRC)." (PMID 38351178, 2024).
colorectal cancer (continued). "According to current study, O-GlcNAcylation of YY1 targets SLC22A15 and AANAT, which promotes carcinogenesis in colorectal cancer cells." (PMID 39050579, 2024). "Here, we identify that Oligo-Fucoidan combined with cisplatin treatment induces ROS signaling in colorectal cancer cells which can be suppressed by antioxidants (NAC, MitoQ and DPI), demonstrating that Oligo-Fucoidan and cisplatin together induce the oxidative signaling axis of YY1/EGFR/MnSOD." (PMID 32059469, 2020).
pancreatic cancer (38 papers, 2014 to 2026). "For instance, in pancreatic cancer, high YY1 expression levels are associated with better clinical outcome for patients, while in colon cancer YY1 was found to promote tumorigenesis." (PMID 35693944, 2022). "In contrast, high expression of YY1 mRNA was associated with a worse outcome in diffuse large B-cell lymphoma (DLBCL) but showed a better outcome in pancreatic cancer." (PMID 33315124, 2021). "We also explored the potential mechanisms underlying the tumor suppression role of YY1 and found that YY1 suppresses invasion and metastasis of pancreatic cancer cells by downregulating MMP10 in a MUC4/ErbB2/p38/MEF2C-dependent mechanism." (PMID 24884523, 2014). "In addition, we explored the function of YY1 in pancreatic cancer using a series of loss-of-function assays." (PMID 36123703, 2022). "Given that the YY1 induction of miR-135b suppresses Bmal1, as shown in pancreatic cancers, YY1 may be important to the loss of circadian regulation of metabolism that is proposed to underpin tumour aetiology as well as ongoing tumour pathophysiology." (PMID 35582450, 2020). "In this study, we implicated YY1 in the regulation of autophagy in pancreatic cancer cells." (PMID 29052509, 2017). "The ability of YY1 to promote apoptosis in pancreatic cancer cells suggests it may represent a valuable diagnostic and therapeutic target." (PMID 27074573, 2016). "Although YY1 also exert other effects, the results of the present study indicate that YY1 promotes apoptosis in pancreatic cancer cells and may represent a valuable diagnostic and therapeutic target." (PMID 27074573, 2016). "The interaction between YY1 and miR-30a illustrates the importance of feedback control in autophagy, and this circuit may constitute a valuable diagnostic and therapeutic target for treating pancreatic cancer." (PMID 29052509, 2017). "Numerous studies have shown increased YY1 expression in various tumor cells, including breast, gastrointestinal, hepatocellular, and pancreatic cancers." (PMID 40867514, 2025). "Another study showed that a transcriptional regulator Yin Yang-1 (YY1) downregulated the expression of CDKN3 by directly binding to the promoter region of CDKN3 in pancreatic cancer cells." (PMID 38356706, 2024). "IHC staining results on consecutive tissue sections from pancreatic cancer patients revealed that tissues with high YY1 expression exhibited elevated expression of FAM60A, and vice versa, further underscoring the expression correlation between YY1 and FAM60A." (PMID 38314086, 2024). "Generally speaking, YY1 plays a tumor promotion role in the majority of cancer types besides pancreatic cancer." (PMID 36880159, 2023). "The activated YY1 downregulates the expression of the tumor suppressor gene miR-489, thereby promoting the migration and metastasis of pancreatic cancer cells." (PMID 36123703, 2022). "ChIP-sequencing studies showed that YY1 directly binds to the promoter region of TPPP/p25 in the case of pancreatic cancer." (PMID 32033023, 2020). "Pancreatic cancer is a highly invasive cancer with poor prognosis, the development of which is inhibited by the transcription factor, Yin Yang 1 (YY1)." (PMID 32033023, 2020). "In our research, we delved into the role of TPPP induced by YY1 in the development and progression of pancreatic cancer." (PMID 31631174, 2019). "Previous studies showed that aberrant YY1 expression is observed in cancers, including colon, breast, liver and pancreatic cancers 23-27." (PMID 31695789, 2019). "Cellular Transwell assays and wound-healing assays showed that the upregulation of TPPP restored the inhibitory effect of YY1 overexpression on the invasion and migration of pancreatic cancer cells." (PMID 31631174, 2019). "Although YY1 plays a tumor promoting role in many cancers, it largely plays a tumor suppressive role in pancreatic cancer." (PMID 31824839, 2019).
pancreatic cancer (continued). "Recent research has found that the transcription factor Yin Yang 1 (YY1) plays an inhibitory role in the development of pancreatic cancer." (PMID 31631174, 2019). "In line with this, high levels of YY1 expression in pancreatic cancer has been shown to have better clinical outcome." (PMID 31824839, 2019). "In the present study, we find that YY1 also promotes autophagy and attenuates pancreatic cancer growth." (PMID 29052509, 2017). "For example, YY1 suppresses cell invasion and metastasis by downregulating MMP10 expression and increases apoptosis through BAX activation in pancreatic cancer cells, suggesting that YY1 functions as a tumor suppressor." (PMID 28412749, 2017). "In our previous study, we showed that YY1 promotes apoptosis and plays a tumor-suppressive role in pancreatic cancer cells." (PMID 29052509, 2017). "Since YY1 has been observed to promote both apoptosis and autophagy in pancreatic cancer, the effect of suppressing tumor growth clearly requires further investigation." (PMID 29052509, 2017). "In summary, we have identified a novel signaling circuit consisting of YY1 and miR-30a, which is required for regulating autophagy in pancreatic cancer cell lines." (PMID 29052509, 2017). "Here, we investigated the function of YY1 in pancreatic cancer cells autophagy and its mechanisms of action." (PMID 29052509, 2017). "Cumulatively, these results suggest that miR-30a acts in a feedback loop to inhibit YY1, thereby regulating autophagy in pancreatic cancer cells." (PMID 29052509, 2017). "In this study, we found that YY1 overexpression increased Bax mRNA and protein expression and thus induced Bax translocation from the cytosol to the mitochondria in pancreatic cancer cells." (PMID 27074573, 2016). "We found that overexpression of YY1 promoted apoptosis and increased the expression and mitochondrial localization of the pro-apoptotic Bax protein in pancreatic cancer cell lines." (PMID 27074573, 2016). "In summary, we found that YY1 overexpression increases apoptosis in pancreatic cancer cells through upregulation of Bax transcription and subsequent translocation of Bax from the cytosol to the mitochondrial membrane, where it is activated." (PMID 27074573, 2016). "Our previous study revealed that YY1 suppresses cell invasion and metastasis in pancreatic cancer by downregulating MMP10 expression." (PMID 27074573, 2016). "The transcriptional regulator Yin Yang-1 (YY1) is a tumor suppressor known to be overexpressed in pancreatic cancer." (PMID 27074573, 2016). "The TUNEL assay results were consistent with the DNA fragmentation assay and Hoechst 33258 staining showing that YY1 over-expression induced apoptosis in BXPC-3 pancreatic cancer cells." (PMID 27074573, 2016). "In this study, we overexpressed YY1 in pancreatic cancer cells and found that it promotes apoptosis via upregulating Bax transcription and subsequent activation of Bax by translocation from the cytosol to the mitochondrial membrane." (PMID 27074573, 2016). "YY1 suppresses invasion and metastasis of pancreatic cancer cells by downregulating MMP10 in a MUC4/ErbB2/p38/MEF2C-dependent mechanism." (PMID 24884523, 2014). "The YY1 high-level overexpression suppresses invasion and metastasis of pancreatic cancer cells by downregulating MMP10 via a MUC4/ErbB2/p38/MEF2C-dependent mechanism." (PMID 24884523, 2014). "A study found a direct association between YY1 and CDKN3 in pancreatic cancer." (PMID 37682177, 2023). "However, YY1 acts as a tumor suppressor gene in pancreatic cancer and nasopharyngeal cancer, and specific clinical drugs targeting YY1 have not yet been discovered." (PMID 37081988, 2023). "On the contrary, the overexpression of miR-30a attenuates the autophagy-promoting effect of YY1, which means that autophagy in pancreatic cancer may be partly regulated by the coordinated YY1/miR-30a regulatory circuit." (PMID 35651786, 2022).